NAGLU (N-acetyl-alpha-glucosaminidase)
Diseases named in the same sentence as NAGLU in open-access papers:
NAGLU is named in the same sentence as 40 diseases in open-access papers, as found by Europe PMC text mining. Sharing a sentence is not in itself a finding about the gene and the disease. The quoted sentences say what the papers report.
Sanfilippo syndrome type B (29 papers, 2009 to 2026). "In family 3, two affected individuals were found to have a missense mutation (c.1694G > A; p.Arg565Gln) in NAGLU, which is associated with Mucopolysaccharidosis type IIIB (Sanfilippo B) (OMIM 252920)." (PMID 39281811, 2024). "The Sanfilippo type B syndrome or MPSIIIB is caused by a mutation of the α-N-acetylglucosaminidase (NAGLU) gene." (PMID 35890374, 2022). "MPS type IIIB causes Sanfilippo syndrome B due to deficient enzyme alpha-N-acetylglucosaminidase (NAGLU) activity." (PMID 34690692, 2021). "Deficiency of NAGLU mainly causes lysosomal accumulation and urinary excretion of HS, which is characteristic of mucopolysaccharidosis type IIIB (MPS-IIIB)." (PMID 35155448, 2021). "NAGLU deficiency leads to a progressive accumulation of partially degraded heparan-sulfate and to the onset of Mucopolysaccharidosis type IIIB (MPS IIIB), an autosomal recessive LSD." (PMID 33800050, 2021). "Recessive mutations in NAGLU are responsible for Sanfilippo syndrome B, also known as mucopolysaccharidosis III disease B (MPS-IIIB)." (PMID 32375870, 2020). "MPS IIIB or Sanfilippo syndrome type B is caused by mutations in the NAGLU gene, which encodes N-acetyl-α-glucosaminidase (EC 3.2.1.50), a lysosomal enzyme of 720 amino acids with six possible glycosylation sites." (PMID 33105639, 2020). "Mucopolysaccharidosis type IIIB (MPS IIIB) is an inherited metabolic disease caused by the deficiency of the enzyme α-N-Acetylglucosaminidase (NAGLU, EC: 3.2.1.50) required for the degradation of the glycosaminoglycan (GAG) heparan sulfate (HS)." (PMID 32111039, 2020). "MPS IIIB, also known as Sanfilippo syndrome type B, is an inherited lysosomal storage disease caused by mutations in the NAGLU gene, which encodes N-acetylglucosaminidase, which normally degrades heparin sulfate." (PMID 30933722, 2019). "Mucopolysaccharidosis (MPS) IIIB is an inherited lysosomal storage disease caused by the deficiency of the enzyme α-N-acetylglucosaminidase (NAGLU) required for heparan sulfate (HS) degradation." (PMID 29348482, 2018). "Mucopolysaccharidosis type IIIB (MPS IIIB) is a rare genetic disorder in which the deficiency of the lysosomal enzyme N-acetyl-α-glucosaminidase (NAGLU) results in the accumulation of heparan sulfate (HS), leading to progressive neurocognitive deterioration." (PMID 26907177, 2016). "Mucopolysaccharidosis (MPS) IIIB is a lysosomal disease due to the deficiency of the enzyme α-N-acetylglucosaminidase (NAGLU) required for heparan sulfate (HS) degradation." (PMID 26147524, 2015). "Mucopolysaccharidosis type IIIB or Sanfilippo syndrome type IIIB (OMIM #252920) is a lysosomal storage disease caused by the presence of biallelic pathogenic variants in the NAGLU gene (17q21.2), resulting in a deficient enzymatic activity of alpha-N-acetylglucosaminidase (NAGLU, E.C. 3.2.1.50)." (PMID 41008709, 2025). "Sanfilippo syndrome type B (mucopolysaccharidosis III B) is a lysosomal storage disease caused by a homozygous or compound heterozygous mutation in the gene N‐alpha‐acetylglucosaminidase (NAGLU) on chromosome 17q21." (PMID 29881562, 2018). "Loss of NAGLU results in the lysosomal storage disease, Sanfilippo syndrome type B." (PMID 19381295, 2009). "Full genetic testing confirmed the diagnosis of Sanfilippo syndrome type B with a deficiency of alpha-N-acetylglucosaminidase caused by a homozygous mutation c.889C>T, p.(Arg297*) in the NAGLU (N-acetyl-alpha-glucosaminidase) gene." (PMID 36415369, 2022). "Mucopolysaccharidosis (MPS) IIIB (Sanfilippo syndrome B; OMIM 252920), is a lysosomal storage disease with progressive neurological signs caused by deficient activity of alpha-N-acetylglucosaminidase (NAGLU, EC 3.2.1.50)." (PMID 32081995, 2020). "Patient ZK, who was diagnosed for Sanfilippo syndrome B, is a compound heterozygote (c.638C>T/c.889C>T) in the NAGLU gene, with a relatively high (about 25%) residual activity of α‐N‐acetylglucosaminidase." (PMID 32578945, 2020).
Sanfilippo syndrome type B (continued). "Patient Z, who was diagnosed for Sanfilippo syndrome B, is a compound heterozygote (c.638C>T/c.889C>T) in the NAGLU gene, with a relatively high (about 25%) residual activity of α‐N‐acetylglucosaminidase." (PMID 32578945, 2020). "Mucopolysaccharidosis IIIB (MPS IIIB) (Sanfilippo Syndrome Type B; OMIM 252920) is an autosomal recessive metabolic disorder caused by mutations in the NAGLU gene, which encode lysosomal enzyme N-acetyl-glucosaminidase." (PMID 31645877, 2019). "Mucopolysaccharidosis type IIIB (MPS IIIB), an inherited lysosomal disorder, is a sub-type of MPS III caused by deficiency of α-N-acetylglucosaminidase (EC 3.2.1.50 [NAGLU]), a lysosomal acid hydrolase that normally degrades heparan sulfate." (PMID 30101150, 2018). "Sanfilippo syndrome type B (mucopolysaccharidosis type IIIB [MPS IIIB]) is a lysosomal storage disorder primarily affecting the brain that is caused by a deficiency in the enzyme α-N-acetylglucosaminidase (NAGLU), leading to intralysosomal accumulation of heparan sulfate." (PMID 30101150, 2018). "Sanfilippo syndrome type B (mucopolysaccharidosis IIIB), caused by inherited deficiency of α-N-acetylglucosaminidase (NAGLU), required for lysosomal degradation of heparan sulfate (HS), is a pediatric neurodegenerative disorder with no approved treatment." (PMID 28664165, 2017). "Background/Objectives: Sanfilippo Syndrome type B or Mucopolysaccharidosis type IIIB (MPS IIIB, OMIM 252920) is a lysosomal storage disease caused by deficiency of alpha-N-acetylglucosaminidase (NAGLU, E.C. 3.2.1.50) due to pathogenic variants in the NAGLU gene (17q21.2)." (PMID 41008709, 2025). "BMN 250 is being developed as an intracerebroventricular (ICV) delivered enzyme replacement therapy (ERT) for the treatment of Sanfilippo syndrome type B (mucopolysaccharidosis IIIB), which results from deficiency in activity of the enzyme alpha-N-acetylglucosaminidase (NAGLU)." (PMID 31942701, 2020). "Sanfilippo syndrome type B (Sanfilippo B; Mucopolysaccharidosis type IIIB) occurs due to genetic deficiency of lysosomal alpha-N-acetylglucosaminidase (NAGLU) and subsequent lysosomal accumulation of heparan sulfate (HS), which coincides with devastating neurodegenerative disease." (PMID 30657762, 2019). "Mucopolysaccharidosis IIIB (MPS IIIB) (Sanfilippo Syndrome Type B; OMIM 252920) is an autosomal recessive metabolic disorder caused by mutations in the NAGLU gene which encode lysosomal enzyme N-acetyl-glucosaminidase, involved in degradation of complex polysaccharide, heparan sulfate." (PMID 31645877, 2019).
lysosomal storage disease (13 papers, 2009 to 2025). A metabolic disorder caused by mutations in proteins critical for lysosomal function, including lysosomal enzymes, lysosomal integral membrane proteins, and proteins involved in the post-translational modification and trafficking of lysosomal proteins. "MPS III is an autosomal recessive lysosomal storage disease caused mainly by missense variants in the NAGLU, GNS, HGSNAT, and SGSH genes." (PMID 38802532, 2024). "Mucopolysaccharidosis type III B (MPS IIIB) is a lysosomal storage disorder caused by mutations in the NAGLU gene encoding N-acetylglucosaminidase." (PMID 30933722, 2019). "The upregulation of LAMP1, lysosomal enzymes (HEXB and NAGLU) as well as autophagy has been found in multiple lysosome storage diseases (LSDs)." (PMID 35215314, 2022). "Mucopolysaccharidosis type IIIB (MPS IIIB or Sanfilippo syndrome B, OMIM #252920) is an autosomal recessive lysosomal storage disorder (LSD) caused by mutations in the gene encoding the lysosomal hydrolase, N-alpha-acetylglucosaminidase (NAGLU or NAG; E.C. 3.2.1.50)." (PMID 23840811, 2013).
Sanfilippo syndrome (13 papers, 2014 to 2024). "A novel missense mutation in exon 3 of the N‐acetyl‐alpha‐glucosaminidase (NAGLU) gene, NM_000263.3: c.587C>T [NP_000254.2: p.Pro196Leu] causing Sanfilippo syndrome, was detected (read depth: 73x)." (PMID 29881562, 2018). "This idea is reinforced by the recent discovery of mutations in the NAGLU gene in Sanfilippo syndrome and PD, resulting in the accumulation of partial HS chains within the lysosomes as a consequence of the disruption of their degradation." (PMID 25617759, 2015). "Mucopolysaccharidosis type IIIB syndrome (Sanfilippo disease) is a rare autosomic recessif disorder caused by mutations in the α-N-acetylglucosaminidase (NAGLU) gene coding for a lysosomal enzyme, leading to neurodegeneration and progressive deterioration of cognitive abilities in affected children." (PMID 34040605, 2021). "Remarkably, the impairment of HS degradation was recently suggested to play a role in α-synuclein accumulation in PD due to the mutation in NAGLU gene (rs2071046), which typically leads to the accumulation of HS in lysosomes in Sanfilippo syndrome, a human storage disorder." (PMID 25617759, 2015). "Mucopolysaccharidosis type III (MPS III, Sanfilippo disease), is a group of 4 autosomal recessive LSDs caused by pathogenic variants in SGSH, NAGLU, HGSNAT and GNS, respectively." (PMID 35646708, 2022). "Mutations in NAGLU and HGSNAT cause the Sanfilippo Syndrome (also called mucopolysaccharidosis Type III) often misdiagnosed with idiopathic developmental delay, attention deficit/hyperactivity disorder and/or ASD." (PMID 28993790, 2017). "Current study applied targeted NGS to Sanfilippo syndrome and reports a new frameshift variant (c.1294-1304 del CTCTTCCCCAA, p.432LeufsX25) in the NAGLU gene in a consanguineous family which subsequently validated by Sanger sequencing and in silico analysis of the putative variant." (PMID 31645877, 2019).
mucopolysaccharidosis (6 papers, 2015 to 2026). A group of autosomal recessive or X-linked inherited lysosomal storage disorders affecting the metabolism of mucopolysaccharides, resulting in the accumulation of mucopolysaccharides in the body. "In this study, using targeted exome sequencing, we identified novel heterozygote mutations in the NAGLU gene in consanguineous parents of a child who was deceased in her 14 years old where the diagnosis of death was mucopolysaccharidosis." (PMID 31645877, 2019). "Sanfilippo type B is a mucopolysaccharidosis (MPS) with a major neuronopathic component characterized by heparan sulfate (HS) accumulation due to mutations in the NAGLU gene encoding alfa-N-acetyl-glucosaminidase." (PMID 36413418, 2023).
breast carcinoma (3 papers, 2022 to 2025). "Two positive targets, XBP1 and NAGLU, were obtained based on the eQTLGen in the analysis of AF and breast cancer (total)." (PMID 39170695, 2024). "Down-regulation of CLN3, CTSD, and NAGLU in TET2 CD cells was further confirmed by RT-qPCR analysis, and expression of these three genes was shown to be anticorrelated with TET2 expression levels in the breast cancer TCGA cohort of patients (n = 1,218), validating our in vitro observations." (PMID 35351824, 2022).
Alzheimer disease (2 papers, 2025 to 2026). A progressive, neurodegenerative disease characterized by loss of function and death of nerve cells in several areas of the brain leading to loss of cognitive function such as memory and language. "A significant increase in NAGLU activity in four cell lines in the presence of glycomimetic MK 8719, a molecule tested in a Phase 1 study in healthy volunteers to treat Alzheimer's disease, was demonstrated." (PMID 41750382, 2026).
atherosclerosis (2 papers, 2021 to 2022). A disease characterized by the build-up of fatty material and calcium deposition in the arterial wall resulting in partial or complete occlusion of the arterial lumen. "Previous studies have shown that deficiency of NAGLU mainly causes several human disease states, including mucopolysaccharidosis IIIB and atherosclerosis." (PMID 36359828, 2022).
epilepsy (2 papers, 2020 to 2023). A brain disorder characterized by episodes of abnormally increased neuronal discharge resulting in transient episodes of sensory or motor neurological dysfunction, or psychic dysfunction. "The affected subjects from Family Fam-01, who presented with severe ID and epilepsy but without behavioral abnormalities, were found to carry a known pathogenic mutation (p.Asp312Asn) in the NAGLU (N-acetyl-alpha-glucosaminidase) gene." (PMID 31969655, 2020).
Parkinson (2 papers, 2022 to 2025). "The authors suggested that allelic changes in NAGLU increased patient susceptibility to developing Parkinson’s disease, likely due to endo-lysosomal dysfunction." (PMID 35216110, 2022). "Another neurodegenerative disease, Parkinson’s disease (PD) was recently linked to mutations in NAGLU (the enzyme deficient in MPSIIIB)." (PMID 35216110, 2022).
cardiac failure (1 paper, 2015). "Overall, our findings demonstrate that NAGLU-/- mice develop heart disease, valvular abnormalities and cardiac failure associated with an impaired lysosomal autophagic flux." (PMID 26147524, 2015).
Epileptic seizures (1 paper, 2020). "Epileptic seizures were also present in families with NAGLU, SLC5A2, POLR3B, and VPS13A mutations, and behavioral and psychiatric symptoms were observed in a family with POLR3B mutations (Fam 03)." (PMID 31969655, 2020).
myocardial hypertrophy (1 paper, 2021). "Furthermore, myocardial hypertrophy, as one of the clinical manifestations of MPS IIIB, is closely related to the abnormal accumulation of lysosomes caused by NAGLU deficiency, which contributes to early mortality." (PMID 35155448, 2021).
neuropathy (1 paper, 2014). A disorder affecting the nervous system that manifests with pain, tingling, numbness, and/or muscle weakness. "Additionally, the substrates of the NAGLU enzyme, including dermatan sulfate and heparan sulfate, are both positive in urine, further suggesting that loss of function mutations in NAGLU leads to abnormal accumulation of sulfate in urine, which may explain the observed neuropathy." (PMID 25466957, 2014).
osteoporosis (1 paper, 2025). A condition of reduced bone mass, with decreased cortical thickness and a decrease in the number and size of the trabeculae of cancellous bone (but normal chemical composition), resulting in increased fracture incidence. "NAGLU is one of the genes that is in the protein–protein interaction network for osteoporosis." (PMID 40104299, 2025).
pneumonia (1 paper, 2018). An acute, acute and chronic, or chronic inflammation focally or diffusely affecting the lung parenchyma, caused by an infection in one or both of the lungs (by bacteria, viruses, fungi, or mycoplasma.). "Autopsy of four NAGLU+/− pigs that experienced sudden death revealed pronounced pathological changes in the lungs, indicating high susceptibility of this organ, which is in agreement with one previous report that the most common cause of death in MPS IIIB patients was pneumonia." (PMID 30257828, 2018).
Splenomegaly (1 paper, 2018). Abnormal increased size of the spleen. "There was no obvious splenomegaly in NAGLU+/− pigs, and histology did not reveal significant abnormality except for slightly larger splenic corpuscles." (PMID 30257828, 2018).
neurodegenerative disease (4 papers, 2019 to 2023). A disorder of the central nervous system characterized by gradual and progressive loss of neural tissue and neurologic function. "Our study also suggests that NAGLU could function as a potential drug target for clinical intervention of aging-related neurodegenerative diseases." (PMID 36430913, 2022).
genetic disorder (3 papers, 2016 to 2020). "Mucopolysaccharidosis type IIIB (MPS IIIB) is a rare genetic disorder caused by loss-of-function mutations in the NAGLU gene." (PMID 30257828, 2018).
metabolic disorder (3 papers, 2019 to 2020). "Mucopolysaccharidosis IIIB (MPS IIIB) is an inherited metabolic disease due to deficiency of α-N-Acetylglucosaminidase (NAGLU) enzyme with subsequent storage of undegraded heparan sulfate (HS)." (PMID 32111039, 2020). "Sanfilippo syndrome B (or mucopolysaccharidosis type IIIB [MPS IIIB]) is a severe inherited metabolic disorder caused by mutations in the NAGLU gene, encoding α‐N‐acetylglucosaminidase." (PMID 32578945, 2020).
cardiac disease (2 papers, 2015 to 2018). "To explore the molecular mechanisms underlying cardiac disease in MPS IIIB, we generated a cellular model of the disease by silencing NAGLU gene expression in H9C2 cardiomyoblasts through a pool of three DNA plasmids carrying different shRNAs against NAGLU mRNA." (PMID 29348482, 2018).
cancer (1 paper, 2022). A tumor composed of atypical neoplastic, often pleomorphic cells that invade other tissues. "Using the Pan-Cancer TCGA dataset gathering RNA-seq data from 11,060 patients, an anticorrelation between TET2 expression and mRNA levels of lysosome proteins was confirmed for CLN3, CTSD, CTSF, CTSZ, IFI30, and NAGLU, suggesting TET2 might down-regulate lysosomal genes in various types of cancer." (PMID 35351824, 2022).
skeletal dysplasia (1 paper, 2018). Any Mendelian diseases that affects growth and development of the skeleton. "NAGLU and CYP26B1 mutations were related to MPS IIIB and skeletal dysplasia, respectively." (PMID 29606097, 2018).
NAGLU also shares sentences with these, for which no sentence is quoted: Lysosomal disease (3 papers); Sandhoff disease (3); Gaucher disease (2); neurological disease (2); attention deficit-hyperactivity disorder (1); Batten disease (1); early onset epileptic encephalopathy (1); gangliosidosis (1); glioma (1); GM1 gangliosidosis (1); GM2 gangliosidosis (1); hydronephrosis (1); Krabbe disease (1); metachromatic leukodystrophy (1); Niemann-Pick disease (1); prostate carcinoma (1); upper respiratory infections (1); uremia (1).